STAT3 (signal transducer and activator of transcription 3)
Diseases named in the same sentence as STAT3 in open-access papers (continued):
Sharing a sentence is not in itself a finding about the gene and the disease.
tumor (continued). "The data support the hypothesis that the STAT3 upregulation expression level difference between the two groups, tumour vs normal, is a molecular feature involved in the GC samples’ response to platinum-based chemotherapy drugs." (PMID 36979673, 2023). "JAK2/STAT3 pathway can regulate tumor occurrence and development." (PMID 36814203, 2023). "For example, the release of cytokines such as IL-23, which may be regulated by STAT3 or by STAT3/NRF2 interplay can promote tumor growth or contribute to immune dysfunction of dendritic cells, following KSHV infection." (PMID 37000324, 2023). "Since STAT3 signaling is primarily responsible for the transcription of IL-10 in GAMs, overactive pSTAT3 expression has been linked to both a worse survival rate for GBM patients and an increase in tumor grade." (PMID 37237548, 2023). "STAT3 deletion can promote Kras driven tumor initiation and progression in mice 26–28." (PMID 36993454, 2023). "Subsequently, we showed that TSN might inhibit tumor development by regulating the phosphorylation level of STAT3." (PMID 37946196, 2023). "Similarly, IL-8 has been shown to promote EMT of HCC tumour cells via the JAK2/STAT3/Snail signalling pathway, and hence induce their migration and invasion." (PMID 37894344, 2023). "Interestingly, STAT3 overexpression has been associated with poor prognosis of OS and the inhibition of JAK2/SATA3 by an inhibitor has shown promising result in OS tumor reduction in nude mice." (PMID 37491298, 2023). "The two tumours with the strongest rise in pAKT also showed an increase in STAT3 phosphorylation." (PMID 37604687, 2023). "Similarly, epithelial ovarian cancer-derived EVs contain high levels of miR-222-3p that can polarize macrophages to M2-like TAMs and thereby favor tumor progression by inducing SOCS3/STAT3 signaling." (PMID 36670988, 2023). "A combined array analysis of DNA methylation and gene expression in human mesenchymal stem cells (MSCs) pre- and post-tumor co-culture reveals that tumor-induced methylation of STAT3 are pivotal for CAF activation and tumor growth, an effect reversible by 5-azacytidine." (PMID 38044445, 2023). "Noticeably, the activation of STAT3 signalling is frequent in several tumours." (PMID 36979673, 2023). "Collectively, the results indicate that NKX2-2 regulates KIAA1429-associated m6A writers, facilitating the positive feedback loop between KIAA1429 and STAT3 and reinforcing ES-dependent epigenetic changes, the malignant cell cycle and tumor-triggered inflammation in ES." (PMID 37759224, 2023). "In addition, STAT3 activation leads to tumor-promoting inflammation and suppresses antitumor immunity." (PMID 37686472, 2023). "Furthermore, a broad inhibitory activity towards tumor-involving protein signaling pathways, such as signal transducer and activator of transcription 3 (STAT3), Notch, nuclear factor κB (NF-κB), and Wnt/β-catenin, are reported in the past decade." (PMID 37242518, 2023). "Expression of VEGFA (p = 0.0110) was higher in high stromal STAT3 tumours." (PMID 37199043, 2023). "Another transcription factor, signal transducer and activator of transcription 3 (STAT3) is aberrantly activated in tumor cells, and it is immunosuppressive in advanced disease stages as a regulator of hypoxia-inducible factors HIF-1α and growth factors to improve cancer development." (PMID 36675114, 2023). "Furthermore, as a critical transcriptional regulator involved in cell proliferation and metastasis, STAT3 plays a vital role in tumorigenesis and tumor development." (PMID 36672337, 2023). "Compared to other STAT family members, STAT3 is highly phosphorylated and may promote tumor development." (PMID 36852795, 2023). "Previous data suggest the effective role of STAT3 in tumor development in breast cancer." (PMID 37620551, 2023). "STAT3 inhibitors have been evaluated in clinical trials for advanced tumor treatment." (PMID 37308559, 2023). "STAT3 knockdown in DCs has been reported to promote their anti-tumor activity." (PMID 38069260, 2023).
tumor (continued). "The elevation of interleukin 6 over-activates the Janus kinase/signal transducer and activator of transcription (JAK/STAT3) signaling pathway, which is responsible for tumor proliferation, invasion, and metastasis, in addition to suppressing the antitumor immune response." (PMID 37445794, 2023). "Therefore, tumorigenic EMT seems to be promoted by a reciprocal immunosuppressive interplay between tumor cells and macrophages, activated by IL-6/JAK/STAT3 signaling during the early phases of tumor progression." (PMID 37190141, 2023). "Studies have demonstrated that PDL1 + T cells have various tolerogenic effects on tumor immunity through different mechanisms, including induced STAT3-dependent ‘back-signaling’ in CD4 + T cells, inhibition of effector T cells via the PDL1-PD1 axis, and engagement with PD1 + macrophages." (PMID 37777797, 2023). "In the present study, we found that DOKD may exert its role in inhibiting CT26+ tumor angiogenesis by inhibiting the STAT3/HIF-1α/VEGFA pathway." (PMID 37239383, 2023). "Athymic nude mice with head and neck squamous cell carcinoma patient-derived xenografts (PDX) and gastric adenocarcinoma PDX were treated with tocilizumab, an anti-IL6Rα antibody that inhibits tumor growth in vivo in part by inhibiting the STAT3 and MEK/ERK signaling." (PMID 38193080, 2023). "Moreover, VEGF can bind to VEGFR on tumor cells, activating STAT3 and facilitating tumor cell proliferation and migration." (PMID 38169837, 2023). "In addition, inhibition of janus kinase 2 (JAK2)/STAT3 was found to reduce MDSCs in the tumor ecosystem through the inhibition of VEGFA and casein kinase 2 (CK2) in HNSCC transgenic mouse models." (PMID 37024932, 2023). "Oral PGG treatment of MDA-MB-231 xenograft nude mice suppressed phosphorylated STAT3 in the tumor tissues and downstream target proteins, including VEGF and Bcl-2, which explained the antiproliferative, pro-apoptotic and antiangiogenesis effects of PGG in a breast cancer mouse model." (PMID 37375411, 2023). "In nude mice transplanted with HCC cells (HepG2 or Huh-7), ectopic expression of C1QTNF1-AS1 led to suppression of HCC tumor growths in vivo which was accompanied by a decrease in the expression of phosphorylated STAT3, as well as an increase in SOCS3 expression." (PMID 37762066, 2023). "Moreover, EGFR also promotes transcriptional activation of signal transducer and activator of transcription 3 (STAT3) in the nucleus via direct interaction and enhances its biological functions such as tumor growth, differentiation, and apoptosis." (PMID 37560308, 2023). "In addition, other studies have found that STAT3 plays a major role in the expansion of regulatory T cells, and regulatory T cells can promote tumor progression by inhibiting the antitumor immune response mediated by TH1 CD4+ T and CD8+ T cells." (PMID 37724127, 2023). "Therefore, it is possible that under one set of conditions the tumor-promoting activities of STAT3 would dominate its cancer-inhibiting functions, whereas in others it would have the opposite effects." (PMID 37190183, 2023). "Consequently, inhibitors targeting the JAK/STAT3 pathway have the potential to impede tumor cell growth and promote antitumor immune responses." (PMID 37637038, 2023). "Consistent with our hypothesis, the Aspiletreins bound to the targets with high affinity and likely inhibited the tumor-promoting functions of STAT3, VEGFA, HSP90AA1, and FGF2 or enhanced tumor-suppressing activity of IL2, or both." (PMID 36707691, 2023). "In addition to IDO1, it has been long known that tumours can suppress immunogenic signals by activating the signal transducer and activator of transcription 3 (STAT3) signalling, which ultimately suppresses DCs maturation." (PMID 37454231, 2023). "Furthermore, STING agonist treatment combined with the STAT3 inhibitor and markedly regressed tumor growth in syngeneic mice by increasing CD8+ T cells and Tregs and MDSCs in TME." (PMID 37006306, 2023).
tumor (continued). "While STAT3 is usually considered an oncogene, some research suggests that it may also have a tumor suppressive effect in certain cases." (PMID 37573301, 2023). "Meanwhile, STAT3 protein increased with the stages of tumor patients." (PMID 38137415, 2023). "In addition, IFN-λ promotes angiogenesis, epithelial-mesenchymal transfer, invasion and migration of tumor cells in a STAT3-dependent manner." (PMID 37697300, 2023). "In addition, lactate-mediated activation of the ERK/STAT3 signaling pathway was determined to perform a crucial role in the pro-angiogenic M2-like polarization of ATMs and subsequent tumor neovascularization." (PMID 37564659, 2023). "The important role of STAT3 in tumor development has been well described." (PMID 37371647, 2023). "Our previous study in mouse tumor models shows that Plasmodium infection significantly downregulates the phosphorylated level of STAT3 (pSTAT3) within MDSCs in tumor tissues and the expression level of TGF-β in tumor tissues, thus releasing the tumor immunosuppressive microenvironment." (PMID 37916167, 2023). "Moreover, WB737 inhibited STAT3 more potently than Stattic, resulting in a significant antitumor effect with undetectable toxicity, followed by almost complete tumor regression in an NKTL xenograft model harboring a STAT3‐activating mutation." (PMID 37334274, 2023). "STAT3 proteins suppress antitumor immunity and accelerate tumor progression." (PMID 37057281, 2023). "Interestingly, although they had a similar proportion of total tumor F4/80+ macrophages, mice treated with the STAT3 inhibitor exhibited an increase in in the proportion of tumor CD146+ macrophages compared with that in control mice." (PMID 37308559, 2023). "Furthermore, we detected the protein levels of p‐JAK2 and p‐STAT3 in tumor tissues collected from HCC xenograft tumor models by IHC." (PMID 37563971, 2023). "YFSJ can reduce the level of inflammation in the tumor microenvironment in vivo, inhibit the abnormal activation of the Stat3/HIF-1α/BNIP3 signaling pathway induced by tumor-related inflammation, thereby inhibiting the overactivation of mitophagy in skeletal muscle, and finally alleviate CRF." (PMID 36814560, 2023). "STAT3 suppression through short interfering RNA (siRNA) has been hypothesized to limit tumor growth." (PMID 37237548, 2023). "Furthermore, they have previously shown tumor cell-derived IL1α induces stromal-derived IL-6, reciprocally activating tumor cell-autonomous STAT3 signaling, a well-known indicator of chemoresistance and oncogenic signaling in PDAC." (PMID 36902166, 2023). "NF-κB and IL-6/STAT3 signalings are important regulators in tumor inflammation." (PMID 37781036, 2023). "Furthermore, STAT3 is involved in multiple aspects of mechanisms governing tumor escape from immune surveillance and is a direct target of miR-506 in PDAC cells." (PMID 38001876, 2023). "Similarly, STAT3 signaling was constitutively activated in tumor-infiltrating immune cells, including DCs, and ablation of STAT3 triggered immune cells to suppress tumor proliferation and metastasis." (PMID 37180168, 2023). "Hence, the evaluation of ICRN on STAT3 downregulation in order to switch M2 to M1 in the tumor microenvironment as well as in cancer stemming cell inactivation can be a promising study in the future." (PMID 36662090, 2023). "Similarly to genome instability, these processes are driven by STAT3 activation (phosphorylation), which orchestrates tumor transformation in the cancer cell." (PMID 37555952, 2023). "As such, overexpression of STAT3 in DC leads to pro-tumor effects within the TME." (PMID 37173951, 2023).
tumor (continued). "In addition, we have reported that miR-1246 increases IL-6 secretion of ECs in highly metastatic tumor EVs, resulting in induction of drug resistance through the activation of STAT3 and Akt." (PMID 37124539, 2023). "IGF/IGF-1R mediates cell survival and induces tumor cell invasion and metastasis by crosstalk with the STAT3 signaling pathway, thereby enhancing tumor cell invasion and metastasis, and IGF/IGF-1R can induce cell migration through the PKD or RhoA/PKC signaling pathway." (PMID 36698167, 2023). "The various regulators of STAT3 expression and the different inducers of its activation may lead to diverse functional effects, which may also be dictated by tumor intra- and inter-heterogeneity." (PMID 37190183, 2023). "Evidence that tumor derived exosomes may package inflammatory cytokines, indicates a potential role of exosomes in the activation of STAT3 signaling." (PMID 36672227, 2023). "Interestingly, the presence of these phosphorylated-STAT3 immunosuppressive astrocytes is induced by tumor and microglia cells." (PMID 37020242, 2023). "As FGFR inhibition reduces the phosphorylation of STAT3, it may indirectly modulate the tumour microenvironment." (PMID 37173994, 2023). "Interestingly, we found that IRF1, STAT1, STAT2, and STAT3 were all significantly downregulated in Scissor+ tumor cells compared to Scissor− and background tumor cells." (PMID 37021816, 2023). "Macrophages could promote cancer stem cells by secreting IL-6 and activating of STAT3 signaling and subsequently contribute to tumor growth." (PMID 37143953, 2023). "Treatment with shSTAT3/lipoplexes reduced STAT3 protein levels and inhibited tumor growth." (PMID 38067351, 2023). "In pathological angiogenesis, DUOX2-induced ROS generation could activate proteins, such as serine/threonine kinase (AKT) and signal transducer and activator of transcription 3 (STAT3), which are known to promote tumor angiogenesis." (PMID 37891879, 2023). "Therefore, macrophage polarization can be regulated by activating or inhibiting the SOCS3-regulated JAK/STAT3 pathway, providing new therapeutic targets for inflammation, fibrosis, tumor and other related diseases." (PMID 37081874, 2023). "STAT3 over-activation induces immunosuppression and tumor invasion." (PMID 38098005, 2023). "Notably, activated STAT3 was more abundant at the tumor invasive front and correlated with metastatic progression of HNSCC." (PMID 36446524, 2023). "More importantly, since IL-6 transcription can be triggered by inflammatory cytokines including TGFβ, IL-1, and TNFα which are also activated mainly by NF-κB and STAT3, IL-6 within the BM microenvironment can create a feed-forward loop to propagate tumour progression." (PMID 37808081, 2023). "We speculate that a low level of IL-6 further diminishes STAT3 activation, thereby reducing tumor progression." (PMID 37686472, 2023). "Persistent STAT3 activation results in tumor formation and poor prognosis in case of malignancies." (PMID 37240202, 2023). "Furthermore, these type 1 IFNs induce granzyme B (Gzm-B) expression in CD8+T cells by STAT3 activation to increase their cytotoxic action against tumor cells." (PMID 37380989, 2023). "Compounds 12a and 13d work in the same way and most pronouncedly affect the STAT5, STAT3, Akt and p38 kinases in the tumor cell at a concentration of 0.006 and 0.004 μM, which affects the number of phosphorylated forms of various kinases compared to the control." (PMID 36765714, 2023). "Furthermore, MDSCs can lead to metastasis and tumor proliferation via the downregulation of STAT3 and the production of VEGF and other essential mediators of tumor angiogenesis." (PMID 37766141, 2023). "Some reports indicate that Toll-like Receptors (TLRs) could stimulate STAT3 activity; this pathway plays a role in tumor development induced by these receptors." (PMID 37372319, 2023).
tumor (continued). "In addition, 9p24.1 copy number amplification is related to the increase of JAK2 and phosphorylated STAT3, which is also observed in tumour specimens from 10 recurrent or refractory Hodgkin’s lymphoma patients." (PMID 36522474, 2023). "Having established PRMT6’s capacity to regulate the IL-6/STAT3 signaling pathway—an essential player in tumor metastasis—it was imperative to delve deeper into whether PRMT6-mediated tumor metastasis hinged on the IL-6/STAT3 signaling pathway." (PMID 37813837, 2023). "Next, we wanted to assess whether PI3K/Akt and JAK/STAT3 signaling inhibition could function as potential treatments targeting PTC tumor progression." (PMID 36982542, 2023). "Mucin 1 (MUC1) can mediate tumor invasion, and its expression depends on STAT3." (PMID 38067351, 2023). "ONA administration also suppressed STAT3 activation in the tumor tissues." (PMID 36961655, 2023). "Many studies have uncovered that certain microbes could not only influence cytokines such as IL‐6 and TNF‐a directly or indirectly, but also activate the NF‐κB pathway or STAT3 pathway to promote tumor progression." (PMID 38868430, 2023). "Activation of STAT3 is significantly correlated with the expression of programmed cell death-ligand 1 (PD-L1), suggesting that STAT3 activation leads to increased PD-L1 expression, promoting immune evasion by the tumor." (PMID 37718386, 2023). "STAT3 is a major regulatory factor in maintaining the stemness of tumor cells." (PMID 37534250, 2023). "KT-333 is a potent degradation agent that specifically degrades undruggable STAT3 in tumor cells." (PMID 37496997, 2023). "Moreover, Src inhibition by dasatinib or tirbanibulin disrupted mammosphere formation in CD96‐overexpressing tumor cells and Stat3 phosphorylation in BCSCs, supporting that CD96 can sustain cancer cell stemness via the Src‐Stat3 pathway." (PMID 36581470, 2023). "STAT3 can regulate cell apoptosis, proliferation, and tumor invasion." (PMID 36814203, 2023). "Similarly, we found that in KIRC, STAT3 promoted tumor proliferation, invasion, and metastasis, and played a prooncogenic role in KIRC." (PMID 37298609, 2023). "Recently, STAT3-targeted inhibitors have become a hot topic in the research of anti-tumor drugs." (PMID 38031104, 2023). "In the tumor microenvironment, numerous cytokines, such as IL-6 and IFNα/β, can activate JAKs by phosphorylating tyrosine residues, which in turn phosphorylate and activate STAT3 to regulate the transcription of downstream target genes." (PMID 37103357, 2023). "In many human tumors, aberrant activation of STAT3 triggers tumor progression through oncogene expression, leading to increased malignancy of the tumor; therefore, targeting STAT3 may improve tumor progression and, thus, suppress tumor immune responses." (PMID 37760803, 2023). "The findings suggested that nuciferine may exert its anti-OSCC effects by inhibiting the tumor-promoting STAT3 signaling pathway to some extent." (PMID 37833979, 2023). "EPHB2 promotes angiogenesis in tumor cells by introducing STAT3 phosphate into the nucleus." (PMID 36376513, 2023). "IL-6 mediates an increase in tumor cell malignancy, which may be related to its activation of the STAT3 signaling pathway." (PMID 37576403, 2023). "The ROCK2/STAT3 pathway has become a major research direction in tumor immunity." (PMID 36982538, 2023). "Systemic administration showed inhibition in the size of tumor, and decreased STAT3 target genes." (PMID 37173951, 2023). "Notably, STAT3 is instrumental in tumor development and in directing the polarization of tumor-associated macrophages." (PMID 37711450, 2023). "The survival of tumor cells depends on STAT3's ability to activate MCL-1." (PMID 36852795, 2023). "Additionally, chrysin had the ability to reduce STAT3 phosphorylation, which inhibits tumor progression and disrupts hypoxia-induced VEGF gene expression." (PMID 36905557, 2023).